RCVRN (recoverin)
Description:
Acts as a calcium sensor and regulates phototransduction of cone and rod photoreceptor cells (By similarity). Modulates light sensitivity of cone photoreceptor in dark and dim conditions (By similarity). In response to high Ca(2+) levels induced by low light levels, prolongs RHO/rhodopsin activation in rod photoreceptor cells by binding to and inhibiting GRK1-mediated phosphorylation of RHO/rhodopsin (By similarity). Plays a role in scotopic vision/enhances vision in dim light by enhancing signal transfer between rod photoreceptors and rod bipolar cells (By similarity). Improves rod photoreceptor sensitivity in dim light and mediates response of rod photoreceptors to facilitate detection of change and motion in bright light (By similarity).
Synonyms: RCV1
Tractability: No criterion of Open Targets' tractability assessment is met for any kind of drug.
Gene: Protein-coding gene on chromosome 17 (9,896,320 to 9,905,271, reverse strand). Ensembl gene ENSG00000109047.
Subcellular location: Photoreceptor inner segment; Cell projection, cilium, photoreceptor outer segment; Photoreceptor outer segment membrane; Perikaryon
Subcellular location (Human Protein Atlas): Mid piece; Principal piece
Pathways (Reactome):
Sensory Perception: Inactivation, recovery and regulation of the phototransduction cascade
Gene Ontology:
Molecular function: calcium ion binding; calcium sensitive guanylate cyclase activator activity
Biological process: regulation of signal transduction; signal transduction; visual perception
Cellular component: perikaryon; photoreceptor inner segment; dendrite; photoreceptor outer segment
Genetic constraint (gnomAD): Loss-of-function variants: 15 observed, 14.16 expected, observed/expected ratio (o/e) 1.06, 90% interval 0.71 to 1.62. The upper end of that interval is the gene's LOEUF score, 1.62, which puts it in group 6 of 6, group 1 being the genes least tolerant of losing a copy. Missense variants: 195 observed, 213.47 expected, observed/expected ratio (o/e) 0.91, 90% interval 0.81 to 1.03. Synonymous variants: 85 observed, 91.82 expected, observed/expected ratio (o/e) 0.93, 90% interval 0.78 to 1.11.
Homologues: Orthologues: chimpanzee RCVRN (100% identical), dog RCVRN (88% identical), mouse Rcvrn (88% identical), rat Rcvrn (88% identical), guinea pig RCVRN (87% identical), rabbit RCVRN (87% identical), pig RCVRN (86% identical), tropical clawed frog rcvrn (80% identical), zebrafish rcvrn2 (63% identical), zebrafish rcvrn3 (56% identical), Caenorhabditis elegans ncs-2 (40% identical), Drosophila melanogaster CG7646 (34% identical), and 2 more. Paralogues in human: HPCA (50% identical), HPCAL1 (49% identical), NCALD (47% identical), HPCAL4 (44% identical), NCS1 (42% identical), VSNL1 (42% identical), KCNIP2 (32% identical), KCNIP3 (32% identical), KCNIP1 (32% identical), GUCA1A (31% identical), GUCA1B (30% identical), KCNIP4 (30% identical), and 2 more.
Diseases named in the same sentence as RCVRN in open-access papers:
RCVRN is named in the same sentence as 84 diseases in open-access papers, as found by Europe PMC text mining. Sharing a sentence is not in itself a finding about the gene and the disease. The quoted sentences say what the papers report.
cancer-associated retinopathy (10 papers, 1996 to 2025). Cancer associated retinopathy (CAR) is a paraneoplastic disease of the eye associated with the presence of extraocular malignancy and circulating autoantibodies against retinal proteins. "Paraneoplastic retinopathy (PR) is a rare autoimmune condition typically associated with progressive visual loss and is often linked to anti-recoverin antibodies." (PMID 39720375, 2024). "The most specific and sensitive antigen associated with paraneoplastic retinopathy is recoverin, a 23-kDa protein involved in the activation and recovery of guanylate cyclase, which influences rhodopsin function." (PMID 39720375, 2024). "As cognitive dysfunction is usually not a main symptom of diseases, such as late-onset ataxia and paraneoplastic retinopathy, we feel compelled to report this novel phenotype associated with recoverin antibodies in our homogeneous patient case series." (PMID 35053759, 2021). "Recently, a photoreceptor protein, recoverin, has been recognised as an autoantigen of cancer-associated retinopathy (CAR), a rare paraneoplastic neurological syndrome often associated with patients with small-cell lung cancer (SCLC)." (PMID 8912538, 1996). "It has been hypothesized that antibodies against recoverin, a protein involved in cancer-associated retinopathy (CAR), or gephyrin, a protein localized in rat retina, could have a role in patients with mixed SPS and retinopathy phenotypes." (PMID 37891730, 2023). "Anti-recoverin antibodies play an important role in paraneoplastic retinopathy, in which degeneration occurs, mainly in patients with small-cell lung cancer." (PMID 40917683, 2025). "Recoverin antibodies are known to be associated with both paraneoplastic and non-paraneoplastic retinopathy and late-onset ataxia without retinopathy." (PMID 35053759, 2021). "In analogy, in cancer-associated retinopathy (CAR), another paraneoplastic autoimmune syndrome in retina, uptake of autoantibodies against intracellular retinal antigens (e.g. recoverin) has been shown to be temperature and actin dependent, consistent with an active endocytic process." (PMID 23936334, 2013).
small cell lung carcinoma (8 papers, 1996 to 2025). Small cell lung cancer (SCLC) is a highly aggressive malignant neoplasm, accounting for 10-15% of lung cancer cases, characterized byrapid growth, and early metastasis. "Antibodies against recoverin are mostly found in paraneoplastic, autoimmune retinopathy and associated malignancies are mainly small cell lung carcinoma and occasionally gynecological tumors; in this patient retinopathy and malignancies were ruled out." (PMID 40746968, 2025). "The etiology is connected to an antibody synthesis against Recoverin, a calcium-binding protein found in retinal photoreceptors, and it is typically associated with small-cell lung cancer." (PMID 36769861, 2023). "In a guinea pig model, animals were sensitized with small cell lung cancer cell lines that induced production of anti-recoverin autoantibodies in the animals and caused retinopathy." (PMID 21031137, 2010). "Recoverin is a protein that is predominantly found in retinal photoreceptor cells, and a 1993 report was the first to find antibodies against recoverin in a middle-aged patient with oat cell lung carcinoma." (PMID 37958968, 2023). "An example of such a response are AAbs against recoverin, a protein normally sequestered in the retina but it is also produced in small cell carcinoma of the lung and other cancers." (PMID 29713325, 2018). "Initially, only patients who had been diagnosed with small cell carcinoma of the lung were found to be seropositive for anti-recoverin AAbs." (PMID 29713325, 2018).
Autoimmunity (7 papers, 2014 to 2025). The occurrence of an immune reaction against the organism's own cells or tissues. "1/5 (20%) had concomitant LGI-1 autoimmunity while the rest were considered as false positive for titin and recoverin." (PMID 38438516, 2024). "Specific cross-reacting autoimmunity against recoverin or collapsin response mediator protein (CRMP)-5 is known to cause cancer-associated retinopathy or paraneoplastic optic neuropathy, respectively." (PMID 24428923, 2014). "Recoverin was found to also be expressed in cancer cells, which may be a critical step for triggering autoimmunity, leading to retinal degeneration." (PMID 40141211, 2025). "We hypothesized a role of recoverin autoimmunity in the pineal gland involving consecutive modulation of hippocampus-based memory caused by an altered release of melatonin." (PMID 35053759, 2021). "Importantly, lymphocyte proliferative responses demonstrated a strong cellular reaction to recoverin, suggesting the validity of recoverin-specific autoimmunity in the pathogenesis of this CAR-like disease, which was then termed “recoverin-associated retinopathy (RAR)”." (PMID 24428923, 2014).
retinal degeneration (7 papers, 2009 to 2025). Degeneration of the retina. "Anti-recoverin antibodies have also been described in association with retinal degeneration." (PMID 39280509, 2024). "We also assessed the retinal degeneration in the rd10 mouse retina treated with PIC-OCT by examining recoverin immunoreactivity, which labels rod and cone photoreceptors." (PMID 38397799, 2024). "In other studies, anti-recoverin autoantibodies induced apoptosis in photoreceptor and bipolar cells, leading to retinal degeneration." (PMID 21031137, 2010). "Previously, we reported a marked increase in number of recoverin-positive cells in the pars plana of adult mice when acquired retinal degeneration was induced by MNU." (PMID 19169413, 2009). "In rd1 mice with inherited retinal degeneration, many recoverin-positive cells were found in the adult pars plana, a proportion of which were generated after retinal histogenesis." (PMID 19169413, 2009). "The induction of acquired retinal degeneration in adult wild-type mice (P30) increased the number of BrdU-positve cells by roughly fourfold and recoverin-positive cells by approximately 17-fold in the pars plana." (PMID 19169413, 2009). "The anti-recoverin antibodies, in this scenario, may then represent the epiphenomenon of retinal degeneration." (PMID 38983022, 2023). "Autoimmune retinopathy should be considered in the differential diagnosis of unusual retinal degeneration in patients with AIRE mutations, and prompt systemic work-up is needed to rule out occult malignancy in those positive for anti-recoverin antibody." (PMID 34122451, 2021).
autoimmune retinopathy (6 papers, 2010 to 2025). An autoimmune disease characterized by sudden onset of photopsias and scotomata in patients with no family history of retinitis pigmentosa, followed by visual field and central vision loss. "Surprisingly, certain autoantibodies have never yet been associated with cognitive impairment, such as the Recoverin antibodies known to mediate autoimmune retinopathy." (PMID 33677623, 2021). "Here we report a 2-year-old Japanese girl with an AIRE gene mutation who developed ALF caused by APAH, as well as autoimmune retinopathy associated with anti-recoverin antibody that emerged before onset of major symptoms led to a diagnosis of APECED." (PMID 34122451, 2021). "The patient also was found to have an autoimmune retinopathy associated with anti-recoverin antibody." (PMID 34122451, 2021). "Here we report a 2-year-old Japanese girl with an AIRE gene mutation who developed APAH with ALF, preceded by autoimmune retinopathy associated with anti-recoverin antibody before major symptoms suggested a diagnosis of APECED." (PMID 34122451, 2021). "Recoverin has been demonstrated to be one of the main causative antigenic retinal proteins common in many cases of autoimmune retinopathy (AIR)." (PMID 21031137, 2010). "Elevated recoverin antibodies were detected in a 47-year-old man with autoimmune retinopathy and SFN after the first dose of BNT162b2." (PMID 41458851, 2025). "Thus, the recoverin-mediated autoimmune retinopathies (CAR, RAR and BAR) and ophthalmic findings in the present case potentially harbor inflammatory features; however, in this cancer patient, it remains unclear why photoreceptors were mostly intact despite the induction of antirecoverin antibody." (PMID 24428923, 2014).
lung carcinoma (5 papers, 1996 to 2025). "One example is recoverin, a photoreceptor-specific protein involved in cancer-associated retinopathy, which may also be expressed in lung carcinoma cells." (PMID 41003888, 2025). "Out of 15 CAR patients with anti-recoverin AAbs eight had lung cancer but only three of those patients had additional anti-67-kDa AAbs." (PMID 24066722, 2013). "We examined the expression of recoverin in human lung cancer cell lines by reverse transcription polymerase chain reaction (PCR), Northern blotting and Western immunoblotting." (PMID 8912538, 1996). "Although anti-recoverin has low sensitivity, it does have high specificity (98%) for lung cancer." (PMID 39897227, 2025).
encephalitis (4 papers, 2019 to 2025). An acute inflammatory process affecting the brain parenchyma. "Here, we found three cases of anti-recoverin associated encephalitis that presented with behavioral symptoms." (PMID 31694559, 2019). "We report a patient with anti-recoverin antibody-positive encephalitis with Cotard and Capgras delusions who was successfully treated with electroconvulsive therapy (ECT)." (PMID 38333894, 2024). "Few reports have described patients with anti-recoverin antibody-positive encephalitis, and no cases of psychosis associated with this encephalitis have been reported." (PMID 38333894, 2024). "Anti-recoverin antibodies in neurological syndromes without retinopathy, i.e., with altered consciousness level, status epilepticus, ataxia, parkinsonism, encephalitis with psychiatric symptoms, and polyradiculopathy/plexopathy, have also been reported." (PMID 40917683, 2025).
Parkinson disease (4 papers, 2021 to 2025). A progressive degenerative disorder of the central nervous system characterized by loss of dopamine producing neurons in the substantia nigra and the presence of Lewy bodies in the substantia nigra and locus coeruleus. "Recoverin autoantibodies were detected in serum in <0.1% in neuropsychiatric and neurological disorders, such as schizophrenia, affective disorders, brain ischemia, Parkinson’s disease, amyotrophic lateral sclerosis, or personality disorder in >2500 patients." (PMID 35053759, 2021).
uveitis (4 papers, 2008 to 2024). An inflammatory process affecting a part of or the entire uvea. "Elevated antibodies against recoverin are usually associated with malignancy and manifest as a paraneoplastic syndrome, predominantly with retinopathy or uveitis, but occasionally also with cerebellar syndrome." (PMID 39280509, 2024). "Subsequently, recoverin was identified as an autoantigen in horses with spontaneous recurrent uveitis." (PMID 39684616, 2024). "A discrepancy between the antigen suspension bead array results for anti-recoverin and the anti-recoverin immunoblot was found in three control patients (one with cataract and two with uveitis)." (PMID 27930731, 2016). "In concordance with previous findings, positive results of serum anti-recoverin autoantibodies were not only observed in patients with presumed (n)pAIR, but also in patients with uveitis and cataract." (PMID 27930731, 2016). "The presence of anti-recoverin autoantibodies was not fully specific for (n)pAIR, since high titres were also present in sporadic patients with cataract (4.8%; p = 0.351) or uveitis (1.3%; p = 0.061)." (PMID 27930731, 2016). "Indeed, recoverin was recognized as one of the unique proteins present in vitreous fluid of patients with noninfectious uveitis." (PMID 39684616, 2024).
Ataxia (3 papers, 2021 to 2025). Ataxia refers to impaired coordination of voluntary muscle movement. "Whether recoverin plays a specific role in generating ataxia is completely unclear, and it is even less likely than recoverin antibodies being involved in cognitive dysfunction." (PMID 35053759, 2021).
Cognitive impairment (3 papers, 2021 to 2022). Abnormal cognition is characterized by deficits in thinking, reasoning, or remembering. "Five patients with cognitive impairment associated with serum recoverin antibodies exhibited profound dysfunctional learning and verbal memory." (PMID 35053759, 2021). "Our case series is dedicated to describing the novel phenotype of cognitive impairment associated with recoverin antibodies." (PMID 35053759, 2021). "As our study sample is too small, no conclusions can yet be made about the diagnostic validity of serum recoverin antibodies in cognitive impairment." (PMID 35053759, 2021). "Furthermore, to differentiate cognitive impairment associated with recoverin antibodies from other potential causes, we thoroughly considered differential diagnoses, including infectious, metabolic, endocrinologic, or mainly neurodegenerative diseases." (PMID 35053759, 2021). "Transferring these findings to our case series, we suggest that T-cells are probably playing a role here as sequelae of an immune process within memory-relevant brain structures related to recoverin antibodies, resulting in our patients’ cognitive impairments." (PMID 35053759, 2021). "We included five patients with cognitive impairment who presented serum recoverin autoantibodies detected by immunoblots in our case series investigation." (PMID 35053759, 2021).
autoimmune uveitis (2 papers, 2014 to 2024). An autoimmune form of uveitis (disease). "Recoverin is reported to be highly uveitogenic and antigenic in rodents and cause experimental autoimmune uveitis (EAU) together with recoverin-specific autoantibody induction and severe photoreceptor degeneration." (PMID 24428923, 2014). "Given that antibodies to recoverin are often detected in the blood of patients with autoimmune uveitis, EAU induced by this protein in rabbits seems be one of the most accurate models of the human disease." (PMID 39684616, 2024). "Released recoverin could similarly modulate cytokine signaling or the function of other secreted proteins, which may contribute to the pathogenesis of autoimmune uveitis." (PMID 39684616, 2024). "Thus, recoverin appears to be the key autoantigen in autoimmune uveitis, especially in birdshot chorioretinopathy." (PMID 39684616, 2024).
breast carcinoma (2 papers, 2013 to 2025). "In this cohort of TULP1 seropositive patients in women with breast cancer (n = 36/90), anti-recoverin (n = 12/90) and anti-Rab6 (n = 13/90) AAbs were found to be present along, with anti-TULP1, in the same patient." (PMID 40141211, 2025). "We discovered that a considerable number of women with breast cancer and vision disturbance had serum anti-TULP1 AAbs, often coexisting with other anti-retinal AAbs, including a case of anti-recoverin and anti-Rab6A being present in the same patient." (PMID 40141211, 2025).
dementia (2 papers, 2021 to 2022). Loss of intellectual abilities interfering with an individual's social and occupational functions. "Our findings suggest a relevant role of recoverin autoimmunity in cognitive dysfunction ranging from MCI to dementia." (PMID 35053759, 2021).
glaucoma (2 papers, 2010 to 2021). Increased pressure in the eyeball due to obstruction of the outflow of aqueous humor. "In the majority of cases the labeled molecules do not react with purified Recoverin, α-enolase, or crystallins, suggesting that these proteins are not major autoantigens in dogs with glaucoma." (PMID 21042562, 2010).
macular edema (2 papers, 2014 to 2022). "This study aimed to investigate the correlation between the severity of photoreceptor damage and the level of anti-retina antibodies (ARAs) in aqueous humor, including recoverin, CA II and enolase-α IgG antibody of macular edema patients." (PMID 36481862, 2022). "We have reported the case of a benign tumor with anti-recoverin antibody-positive retinopathy manifesting typical CAR (i.e., photoreceptor degeneration) and retinal vasculitis with macular edema." (PMID 24428923, 2014).
mastitis (2 papers, 2024). Inflammation of breast tissue during lactation or postpartum due to an obstructed duct or infection. "The network analysis showed that the CSF1R, RHO, RCVRN, CAV3, and GATA4 genes were core nodes, suggesting that these genes could serve as candidate molecular markers for mastitis." (PMID 38674399, 2024). "Notably, the lncRNA-miRNA-mRNA ternary co-expression network of RHO, RCVRN, CSF1R, CAV3, and GATA4 genes is likely to be involved in the regulation of mastitis in Xinjiang brown cattle." (PMID 38674399, 2024).